TET3 (tet methylcytosine dioxygenase 3)
Description:
Dioxygenase that catalyzes the conversion of the modified genomic base 5-methylcytosine (5mC) into 5-hydroxymethylcytosine (5hmC) and plays a key role in epigenetic chromatin reprogramming in the zygote following fertilization. Also mediates subsequent conversion of 5hmC into 5-formylcytosine (5fC), and conversion of 5fC to 5-carboxylcytosine (5caC). Conversion of 5mC into 5hmC, 5fC and 5caC probably constitutes the first step in cytosine demethylation (By similarity). Selectively binds to the promoter region of target genes and contributes to regulate the expression of numerous developmental genes. In zygotes, DNA demethylation occurs selectively in the paternal pronucleus before the first cell division, while the adjacent maternal pronucleus and certain paternally-imprinted loci are protected from this process. Participates in DNA demethylation in the paternal pronucleus by mediating conversion of 5mC into 5hmC, 5fC and 5caC. Does not mediate DNA demethylation of maternal pronucleus because of the presence of DPPA3/PGC7 on maternal chromatin that prevents TET3-binding to chromatin (By similarity). In addition to its role in DNA demethylation, also involved in the recruitment of the O-GlcNAc transferase OGT to CpG-rich transcription start sites of active genes, thereby promoting histone H2B GlcNAcylation by OGT. Binds preferentially to DNA containing cytidine-phosphate-guanosine (CpG) dinucleotides over CpH (H=A, T, and C), hemimethylated-CpG and hemimethylated-hydroxymethyl-CpG.
Synonyms: MGC22014; hCG_40738; BEFAHRS
Tractability: Small molecule: a high-quality ligand is known. PROTAC: UniProt records ubiquitination sites on it; ubiquitination databases record sites on it; a small molecule that binds it is known.
Target class: Enzyme; Oxidoreductase
Gene: Protein-coding gene on chromosome 2 (73,984,910 to 74,108,177, forward strand). Ensembl gene ENSG00000187605.
Subcellular location: Nucleus; Cytoplasm; Chromosome
Subcellular location (Human Protein Atlas): Nucleoplasm; Cytosol; Vesicles
Pathways (Reactome):
Developmental Biology: Chromatin modifications during the maternal to zygotic transition (MZT)
Gene expression (Transcription): TET1,2,3 and TDG demethylate DNA
Gene Ontology:
Molecular function: DNA 5-methylcytosine dioxygenase activity; methyl-CpG binding; protein binding; RNA polymerase II cis-regulatory region sequence-specific DNA binding; zinc ion binding; 2-oxoglutarate-dependent dioxygenase activity; DNA binding
Biological process: positive regulation of transcription by RNA polymerase II; protein O-linked glycosylation; epigenetic programing of male pronucleus; positive regulation of gene expression via chromosomal CpG island demethylation; epigenetic regulation of gene expression; regulation of gene expression
Cellular component: chromosome; cytoplasm; male pronucleus; nucleus; female pronucleus
Genetic constraint (gnomAD): Loss-of-function variants: 19 observed, 130.95 expected, observed/expected ratio (o/e) 0.15, 90% interval 0.1 to 0.21. The upper end of that interval is the gene's LOEUF score, 0.21, which puts it in group 1 of 6, group 1 being the genes least tolerant of losing a copy. Missense variants: 1,866 observed, 2,336.5 expected, observed/expected ratio (o/e) 0.8, 90% interval 0.77 to 0.83. Synonymous variants: 1,037 observed, 974.6 expected, observed/expected ratio (o/e) 1.06, 90% interval 1.01 to 1.12.
Gene-disease validity (ClinGen):
ClinGen rates the evidence that TET3 causes each of these diseases.
Beck-Fahrner syndrome (autosomal dominant): Definitive.
Beck-Fahrner syndrome (autosomal recessive): Limited.
Homologues: Orthologues: chimpanzee TET3 (99% identical), macaque TET3 (98% identical), dog TET3 (93% identical), guinea pig TET3 (92% identical), pig TET3 (91% identical), rat Tet3 (90% identical), rabbit TET3 (90% identical), mouse Tet3 (90% identical), tropical clawed frog tet3 (53% identical), zebrafish tet3 (43% identical). Paralogues in human: TET2 (28% identical), TET1 (25% identical).
Diseases named in the same sentence as TET3 in open-access papers:
TET3 is named in the same sentence as 173 diseases in open-access papers, as found by Europe PMC text mining. Sharing a sentence is not in itself a finding about the gene and the disease. The quoted sentences say what the papers report.
breast carcinoma (17 papers, 2014 to 2025). "While TET2 and TET3 have the potential to influence estrogen receptors and luminal-like transformation in breast cancer, TET1 appears to be more associated with hormone-independent breast cancer." (PMID 39201247, 2024). "Our finding shows the downregulation of TET3 also contributes to 5hmC loss in breast cancer tissues." (PMID 36230901, 2022). "Global loss of 5-hmC is found to be associated with the downregulation of TET1 and TET3 genes in breast cancer." (PMID 36230901, 2022). "In addition to TET1, we report here that TET3 is also associated with a global loss of 5-hmC in breast cancer." (PMID 36230901, 2022). "TET3 was significantly increased in luminal B breast cancer patients with expression of hormone receptors." (PMID 38499584, 2024). "Based on the results presented in the manuscript, breast cancer leukocytes were characterized by increased mRNA expression of TET3 and decreased level of 5-hmC." (PMID 38499584, 2024). "Breast cancer patients had significantly higher TET3 expression level, lower 5-mC and 5-hmC DNA levels." (PMID 38499584, 2024). "In line with the last finding, we have shown that leukocyte expression level of TET3 is higher in breast cancer patients than in the control group." (PMID 38499584, 2024). "Previous studies have reported that TET3 expression is decreased in breast cancer tissues and the MCF-7 cell line in comparison to heathy tissue counterparts and the HLB-100 breast cell line, respectively." (PMID 39201247, 2024). "We found increase of TET3 (p < 0.001) expression level in leukocytes of breast cancer group in comparison to healthy subjects." (PMID 38499584, 2024). "However, in contrast to those findings, expression of TET3 is increased in mononuclear cells from peripheral blood obtained from breast cancer patients compared to healthy subjects’ cells." (PMID 39201247, 2024). "Moreover, TET3 expression was lower in leukocytes from patients with more severe grade of breast cancer (p=0.045)." (PMID 38499584, 2024). "Moreover, our study shed new light on potential estrogen/progesterone modulation of TET3 as it was significantly increased in luminal B breast cancer patients." (PMID 38499584, 2024). "Hence, it could be suggested that TET3 expression and 5-hmC level may have the potential to serve as prognostic markers of breast cancer." (PMID 38499584, 2024). "In breast cancer, hypoxia induced upregulation of TET1/TET3 transcription and increased 5hmC levels were reported to drive metastatic transformation and poor prognosis." (PMID 40241172, 2025). "Analysis of the public TCGA and CBCGA datasets revealed that TET3 expression levels were higher in TNBC relative to luminal‐ and HER2+ types of breast cancer." (PMID 40546127, 2025). "Another study, which concerns peripheral blood samples of breast cancer patients has revealed the increase in only TET2 and TET3 expression." (PMID 38499584, 2024). "In addition, although hypoxia reduces TET enzymatic activity in cancer cells, hypoxia-induced increase of the 5-hmC level locally in the genomic region containing TNF-α gene of breast cancer cells is mediated by TET1 and TET3." (PMID 40764968, 2025). "Furthermore, in breast cancer cell lines MCF-7 and MDA-MB-231, shRNA-mediated depletion of TET1 or TET3 would reduce the expression of mesenchymal genes N-cadherin and vimentin during hypoxia." (PMID 40764968, 2025). "For instance, TET1 and TET3 play a positive role in maintaining breast tumor-initiating cell phenotypes through the TET-TNFα-p38-MAPK axis, as evidenced by the CD44+/CD24− expression, a recognized biomarker of breast cancer stem cells." (PMID 40014756, 2025). "Moreover, breast cancer cells with expression of ESR, PGR, or GPER showed higher levels of TET3 after 4-HT treatment, but in triple-negative cells (MDA-MB-231), TET3 was deceased upon 4-HT supplementation." (PMID 39201247, 2024).
breast carcinoma (continued). "One of the most interesting observations in our study was significantly higher expression of TET3 in luminal B breast cancer patients in comparison to non-luminal HER2 positive breast cancer patients as well as in healthy subjects." (PMID 38499584, 2024). "Moreover, TET3 knocked-down cells under normoxia exhibited an identical alternative splicing pattern of ESRP1 targets (hMENA, SLK, SCRIB, RALGPS2, SLC37A2, FNIP1, CD44, and ARHGEF1) as the hypoxic breast cancer cells." (PMID 34362878, 2021).
diabetes (15 papers, 2018 to 2025). "We also found that AGRP neuron–specific TET3 knockdown caused hyperphagia, obesity, and diabetes in both female and male mice, highlighting a central role of TET3 in regulating feeding, body weight, and glucose metabolism by AGRP neurons." (PMID 36189793, 2022). "AGRP neuron–specific TET3 knockdown causes hyperphagia, obesity, and diabetes." (PMID 36189793, 2022). "Given that CRISPR-mediated deletion of Lepr in adult AGRP neurons causes hyperphagia, obesity, and diabetes, we hypothesized that TET3 might affect leptin signaling in AGRP neurons." (PMID 36189793, 2022). "These factors may cause the increase of TET1 and decrease of TET3 expression levels, which become possible intervention points for the prevention and treatment of diabetes and its complications." (PMID 30574144, 2018). "They further demonstrated decreased levels of TET3 mRNA and TET3 protein in endothelial progenitor cells as biomarkers to evaluate angiopathy in patients with diabetes." (PMID 40599235, 2025). "The strong positive correlation between obesity/diabetes and increased muscle TET3 expression in both humans and mice suggests a role for TET3 in regulation of muscle insulin sensitivity." (PMID 38216792, 2024). "We have reported aberrantly increased expressions of TET3 in hepatocytes of obesity, diabetes and liver fibrosis and that hepatic oxidative stress downregulates let-7 leading to de-repression of TET3." (PMID 37898449, 2023). "For early diagnosis, TET3 can be used as a biomarker to predict the development of diabetes in the offspring." (PMID 36209147, 2022). "Additionally, a recent study by Liu and colleagues revealed elevated muscle TET3 expression in humans and mice with obesity/diabetes, substantiating a robust positive correlation between obesity/diabetes and elevated muscle TET3 expression." (PMID 40620794, 2025). "Increased TET3 expression was also detected in myocytes from individuals with diabetes." (PMID 38216792, 2024). "Our results thus reveal an important role of the hepatic let-7/TET3/HNF4α axis in mediating the therapeutic effects of metformin and suggest that targeting this axis may be a potential therapeutic for diabetes." (PMID 35344434, 2022). "We have previously shown that TET3 expression is aberrantly elevated in the livers of humans and mice with type 2 diabetes and that liver-specific, siRNA-mediated TET3 knockdown improves glucose homeostasis both in dietary and genetic mouse models of diabetes." (PMID 36189793, 2022). "Next, we asked whether muscle TET3 expression would change in mice with obesity and diabetes." (PMID 38216792, 2024). "This research aims to understand the role of TET3, a member of the ten-eleven translocation (TET) family dioxygenases, in PGC-1α dysregulation in skeletal muscles in obesity and diabetes." (PMID 38216792, 2024). "Together, these data demonstrate that obesity and diabetes negatively modulate the glomerular expression of TET1 and TET3 only in females." (PMID 37091852, 2023). "These genes are found in pathways involving Mtor signaling, circadian entrainment, sleep, diabetes, and cholesterol, including genes from the imprinted KOS/TS locus and the epigenetic enzyme Tet3." (PMID 29691382, 2018). "Here, we compared the mRNA and protein levels of TET1, TET2, and TET3 in non-diabetic (ND) control subjects, patients with only type 2 diabetes only (D), and patients with diabetes peripheral artery disease (D-PAD)." (PMID 30574144, 2018). "Here, we report that in adult mouse AGRP neurons, CRISPR-mediated genetic ablation of Tet3, not previously known to be involved in central control of appetite and metabolism, induced hyperphagia, obesity, and diabetes, in addition to a reduction of stress-like behaviors." (PMID 36189793, 2022). "The expression of TET3 (but not TET1 and TET2) mRNA was significantly increased in skeletal muscle tissues of humans with diabetes as compared with non-diabetic control counterparts." (PMID 38216792, 2024).
glioma (15 papers, 2017 to 2025). A benign or malignant brain and spinal cord tumor that arises from glial cells (astrocytes, oligodendrocytes, ependymal cells). "In glioma, reduction in TET3 expression was associated with a genome-wide reduction in 5-hmC levels compared to normal brain, and decreased TET3 expression correlated with poorer prognosis." (PMID 33842321, 2021). "We showed that the plasma relative mRNA level for TET1 was decreased in every stage of glioma, while the TET3 level remained unchanged." (PMID 35494033, 2022). "Quantitative real-time PCR was performed to examine the mRNA expression of TET family genes (TET1, TET2, and TET3) in 34 samples, including 6 Grade II gliomas, 7 Grade III gliomas and 21 Grade IV GBM." (PMID 35494033, 2022). "The upregulation of TET3 was proven to elevate the 5-hmc levels of the promoter regions of c-Myc and promoted the progression of glioma." (PMID 35757739, 2022). "Third, STAT3 is a transcription factor shown to physically interact with TET3 in human glioma cells." (PMID 36189793, 2022). "TET1 and TET3 bind to Oct4 and Nanog regulatory regions and increase the activity of each transcription factor, thereby promoting the reprogramming of glioma cells to glioma stem cells." (PMID 33585477, 2021). "One in vitro study reported the effects of ascorbate on epigenetic marks in LN229 glioma cells, showing increased TET3 mRNA expression, as well as increased 5-hmC, but these cells did not harbor an IDH mutation." (PMID 33842321, 2021). "TET1 expression is upregulated in glioblastomas, TET2 is downregulated in gliomas, and TET3 is epigenetically repressed in gliomas." (PMID 33461542, 2021). "TET1 is elevated in GBM, while TET2 expression is downregulated in glioma, and TET3 is epigenetically repressed in glioma." (PMID 32244981, 2020). "We therefore investigated the potential of the exosomes to alter recipient cells, by profiling gene expression changes in NSCs resulting from GSC exosome treatment, and detected down-regulated expression of glioma-associated tumor suppressors PTEN and TET3." (PMID 29163818, 2017). "We found that TET1, TET2, TET3 mRNA, and 5-hmC levels were decreased during glioma grades." (PMID 35494033, 2022). "Based on the described glia phenotypes in Tet[MI03920]/Tet[null] flies, we wanted to investigate whether expressing TET3, the closest human homologues of dTet, in Drosophila, would recapitulate some glioma like phenotypes." (PMID 35396259, 2022). "Their downregulation was significantly higher in Grade IV GBM in comparison with Grade II gliomas (TET1 and TET3 p < 0.001, TET2 p < 0.01) and Grade III gliomas (TET1 p < 0.001, TET2 and TET3 p < 0.01)." (PMID 35494033, 2022). "Prasad and colleagues demonstrated that hypoxic environment could induce the demethylation in glioma cells by overexpression of TET1 and TET3, then promoted the stemness of tumor cells by upregulating OCT4 and NANOG expression." (PMID 32014008, 2020). "That suppression of TET2 and TET3 in GSC6 leads to attenuated proliferation under conditions of DNA damage suggests that they play a direct role in modulating the DNA damage response process and may contribute to the chemo−/radio-resistance of glioma stem cells." (PMID 29587824, 2018).
liver fibrosis (14 papers, 2016 to 2025). "Chronic overexpression of TET3 is linked to various inflammatory conditions, including type 2 diabetes and liver fibrosis, suggesting a broader involvement of TET3 in inflammatory processes." (PMID 39484721, 2024). "Conversely, TET3 is implicated in the pathogenesis of liver fibrosis, with its increased expression potentially exacerbating the progression of liver fibrosis." (PMID 39195573, 2024). "We investigated the diagnostic accuracy of serum TET3 as a non-invasive screening tool for liver fibrosis." (PMID 37076545, 2023). "With the cut-off value of TET3 set to 194.41 ng/mL, the positive predictive value was 98.60% and the negative predictive value was 71.80% for predicting the risk of liver fibrosis." (PMID 37076545, 2023). "After accepting TET3 as a reliable biomarker, we plotted an ROC curve to show that the AUROC values of TET3 when used to predict the risk of liver fibrosis and cirrhosis were 0.916 and 0.863, respectively." (PMID 37076545, 2023). "We have previously established that chronic TET3 overexpression in human and mouse skeletal myocytes and liver hepatocytes and hepatic stellate cells is associated with insulin resistance, type 2 diabetes, and liver fibrosis." (PMID 39141428, 2024). "Our previous studies demonstrated that TET3 expression is upregulated in human and mouse hepatocytes and hepatic stellate cells during liver fibrosis and that TET3 epigenetically enhances TGF-β1 expression." (PMID 40794443, 2025). "The areas under the ROC curve of the TET3 and fibrosis-4 index for liver fibrosis were 0.863 and 0.813, and 0.916 and 0.957 for liver cirrhosis." (PMID 37076545, 2023). "Collectively, the data identified that TET3, as a direct target of miR‐488-5p, were remarkably upregulated in activated HSCs, liver fibrosis models and fibrotic liver specimens from the patients." (PMID 36001230, 2023). "Taken together, our results show that let-7 is effective in mitigating CCl4-induced liver fibrosis likely by simultaneously targeting the TET3/TGF-β and the FAS-mediated pathways in hepatocytes." (PMID 37898449, 2023). "We highlight that miR-488-5p restrains the activation of HSCs and hepatic fibrosis via targeting TET3 which is involved in the TGF-β/Smad2/3 signaling pathway." (PMID 36001230, 2023). "Meanwhile, some studies have put attention on the role of TET3 in fibrosis, especially hepatic fibrosis." (PMID 36001230, 2023). "The FIB-4 index had lower predictive efficacy for liver fibrosis than TET3 level, but higher predictive efficacy for liver cirrhosis than TET3 level." (PMID 37076545, 2023). "With an optimal cut-off value of 194.41 ng/mL, TET3 level had a high positive predictive value (PPV) of 98.60% and a negative predictive value (NPV) of 71.80% for predicting the risk of liver fibrosis." (PMID 37076545, 2023). "According to univariate analysis, platelet count, FIB-4 index and TET3 level were identified as independent predictors for liver fibrosis." (PMID 37076545, 2023). "TET3 inhibition induced by the overexpression of miR-488-5p reduced extracellular matrix deposition, which contributed to mitigating mouse liver fibrosis." (PMID 36001230, 2023). "The accuracy of the TET3-FIB-4 model to predict liver fibrosis and cirrhosis was significantly better than that of TET3 or the FIB-4 index alone." (PMID 37076545, 2023). "The combination of TET3 and fibrosis-4 index had a highly promising positive predictive value for detecting liver fibrosis and cirrhosis different stages of (93.5% and 100%) as compared with each diagnostic tool alone." (PMID 37076545, 2023). "The TET3-fibrosis-4 model enhances discriminatory power and represents a promising non-invasive tool for the diagnosis and screening of liver fibrosis." (PMID 37076545, 2023). "The inhibition of TET3 signaling attenuates hepatic fibrosis by abrogating the positive feedback loop TET3/TGF-β1 to promote pro-fibrotic gene expression." (PMID 37189665, 2023).